PCSK9 (proprotein convertase subtilisin/kexin type 9)
Diseases named in the same sentence as PCSK9 in open-access papers (continued):
Sharing a sentence is not in itself a finding about the gene and the disease.
atherosclerosis (continued). "Our aim was to evaluate the effect of PCSK9-i on inflammatory biomarkers, neutrophil-to-lymphocyte ratio, monocyte-to-high-density lipoprotein ratio (MHR), and on early atherosclerosis damage analyzed by pulse wave velocity (PWV) in a cohort of FH subjects." (PMID 33745063, 2021). "Release of ICAM-1 from vascular endothelial cells was reduced with PCSK9i alirocumab and anti-PCSK9 vaccine AT04 in the APOE∗3Leiden.CETP transgenic mouse model for hyperlipidemia and atherosclerosis." (PMID 34336112, 2021). "PCSK9 mAbs significantly reduce the level of plasma LDL-C, effectively reducing the incidence of atherosclerosis." (PMID 32169071, 2020). "One rare example of success is the development of PCSK9 monoclonal antibodies (mAbs) (alirocumab and evolocumab) in mice, which contributes to proven therapy for high LDL cholesterol (LDLc) levels and atherosclerosis in humans." (PMID 32714944, 2020). "Proprotein convertase subtilisin/kexin type 9 (PCSK9), a proinflammatory mediator involved in atherosclerosis, is also produced by visceral fat." (PMID 32565719, 2020). "Consistent with this notion, a recent publication revealed that triple combination treatments of statins and antibodies targeting PCSK9 and ANGPTL3 yielded additive effects on cholesterol and atherosclerosis reductions in mice." (PMID 32646941, 2020). "Likewise, although it is widely accepted that the association between PCSK9 and atherosclerosis is dependent on PCSK9-mediated modulation of LDL metabolism, there is a lot of evidence suggesting that PCSK9 may also exert direct cholesterol-independent pro-atherosclerotic effects." (PMID 32460779, 2020). "Therefore, a potential mechanism by which PCSK9 regulates atherosclerosis could target RCT." (PMID 32169071, 2020). "PCSK9 inhibition decreased total cholesterol in serum of APOE*3Leiden.CETP mice and prevented the development of atherosclerosis." (PMID 31366894, 2019). "Proprotein convertase subtilisin/kexin type 9 (PCSK9), which plays a crucial role in lipoprotein metabolism, has been also regarded as an important marker for atherosclerosis." (PMID 29343301, 2018). "The interaction between PCSK9 and LDL-R favors the entry of inflammatory monocytes into the arterial wall and thus promotes atherosclerosis." (PMID 29770231, 2018). "We thank Dr. Hanjoong Jo for the generous gift of PCSK9 AAV and control AAV used in the atherosclerosis study." (PMID 29158473, 2017). "The protein complex proprotein convertase subtilisin/kexin type 9 (PCSK9) serves as an important target for the prevention and treatment of atherosclerosis and lipid homeostasis." (PMID 29296222, 2017). "Plasma levels of proprotein convertase subtilisin/kexin type 9 (PCSK9), apolipoprotein C-III (apoC3) and small dense low density lipoprotein cholesterol (sdLDL-C), have been recently recognized as circulating atherosclerosis-related lipid measurements." (PMID 27713142, 2017). "In animal models of atherosclerosis, PCSK9 inhibition resulted in significant lowering of plasma LDL‐C levels and diminished atherosclerosis progression." (PMID 26493158, 2016). "If elevated plasma PCSK9 contributes to the risk of thrombosis and MI, rather than or in addition to the risk of atherosclerosis, then this could also account for the disproportionate reduction in MI risk associated with genetic variants that lower plasma PCSK9 levels." (PMID 25180781, 2014).
atherosclerosis (continued). "This review delineates these non-canonical mechanisms, emphasizing PCSK9's roles in vascular inflammation, atherosclerosis, thrombosis, regulated cardiomyocyte death, and calcific aortic valve disease (CAVD)." (PMID 41918565, 2026). "Inhibition of PCSK9 with SBC-115076 alleviates lipid accumulation and reduces atherosclerosis severity, indicating that PCSK9 inhibition has therapeutic potential in HHcy-driven atherosclerosis." (PMID 39898976, 2025). "Previous studies of the PCSK9 minipig have also shown development of advanced plaques but in the context of mostly non-obstructive atherosclerosis including fatty streaks." (PMID 40131655, 2025). "Other clinical trials have reported that the use of statins (rosuvastatin), proprotein convertase subtilisin/kexin type 9 inhibitors (PCSK9), and some anti-inflammatory drugs (colchicine) have the potential to stop the progression or even regress atherosclerosis." (PMID 39807445, 2025). "The findings suggest that PCSK9 inhibitors, when combined with statins, not only improve lipid metabolism but also reduce arterial stiffness, offering potential benefits for vascular health in patients with ACS and atherosclerosis." (PMID 40821628, 2025). "PCSK9 and IL6R are current therapeutic targets under investigation for atherosclerosis." (PMID 40649979, 2025). "PCSK9 activates PKCδ, Syk and NF-κB, promoting atherosclerosis progression independently of LDL-R.In apoE-/- mice, the inactivation of PCSK9 has been shown to effectively suppress vascular inflammation and atherosclerosis by reducing the TLR4/NF-κB signaling pathway." (PMID 40354375, 2025). "Currently, inhibition of PCSK9 with human monoclonal antibodies is considered one of the most effective second-line treatments to lower LDL-C in adults with familial hypercholesterolaemia and atherosclerosis." (PMID 39364866, 2025). "Additionally, MYD88-dependent activation in aortic endothelial cells increases PCSK9 (proprotein convertase subtilisin/kexin type 9) expression, suggesting a role for MYD88 in promoting atherosclerosis by affecting endothelial lipid processing." (PMID 38610757, 2024). "In terms of atherosclerosis (hardening of arteries), the effects of circulating PCSK9 are not completely clear." (PMID 39479289, 2024). "Fourth, CCL18 administration in hyperlipidemic CCR6−/− mice neither did aggravate atherosclerosis nor did induce T-cell accumulation in plaque, unlike WT mice that rendered hyperlipidemic by PCSK9 gene transfer." (PMID 38807599, 2024). "Recent research has uncovered that PCSK9 inhibitors not only reduce LDL-C levels but also may positively influence endothelial function, a key early indicator of atherosclerosis and CVD." (PMID 39650150, 2024). "PCSK9 is also secreted by vascular smooth muscle cells, which exhibit enhanced proliferation, migration, and foam cell formation induced by oxidized LDL, thus aggravating atherosclerosis." (PMID 39139638, 2024). "Among 3708 European patients asymptomatic for cardiovascular diseases, PCSK9 plasma levels did not correlate with vascular damage and/or subclinical atherosclerosis of extracranial carotid arteries." (PMID 38402551, 2024). "Therefore, elevated levels of PCSK9 in the blood can lead to higher levels of LDL-C in the blood, and as plasma LDL-C is the most important factor in the development and progression of atherosclerosis, high levels of PCSK9 can contribute to the disease." (PMID 39247108, 2024).
atherosclerosis (continued). "Mest, Adipoq, Ccl2, and Pcsk9 emerged in the differentially expressed genes of the liver and plasma of PM2.5 model mice, which might mediate atherosclerosis accelerated by PM2.5." (PMID 37888673, 2023). "The pro-inflammatory effect of PCSK9 in atherosclerosis is independent of its hyperlipidemic action." (PMID 36831039, 2023). "Unlike ezetimibe, PCSK9 inhibitors are emerging “players” in the field of atherosclerosis, and real-world data on their safety and effectiveness are still being accumulated." (PMID 37175766, 2023). "Several recent studies have indicated that there may be interactions between PCSK9 and the NLRP3 inflammasome, which may contribute to the inflammatory response that drives atherosclerosis development and progression." (PMID 36911736, 2023). "Then, we review current knowledge on how PCSK9 inhibitors reduce atherosclerosis initiation and progression in patients without cancer and the main molecular pathways involved." (PMID 36900189, 2023). "PCSK9 (proprotein convertase subtilisin/kexin type 9), HSP65, and ApoB are some of the possible antigens that may be used as atherosclerosis vaccine antigens." (PMID 37373933, 2023). "According to preclinical research, PCSK9 has pleiotropic effects beyond regulating plasma LDL-C levels and may be a crucial factor in the pathogenesis of atherosclerosis." (PMID 36232177, 2022). "Furthermore, deletion of PCSK9 in mice resulted in decreased lipid and apoB levels and atherosclerotic LDL reduction, and reduced atherosclerosis." (PMID 36470666, 2022). "Additionally, several studies also suggested that the role of PCSK9 in atherogenesis was intertwined with inflammation and the interacting effect shown between PCSK9 and LOX-1 was involved in the inflammatory response of atherosclerosis." (PMID 35252378, 2022). "Regulation of cholesterol-rich LDL level is not the only role that PCSK9 has in atherosclerosis pathogenesis." (PMID 36324757, 2022). "The effects of PCSK9 on atherosclerosis burden are consistent with the observed plasma non-HDL-C concentrations." (PMID 36243100, 2022). "We first examined aortas isolated from WT and suPARTg mice that did not undergo Pcsk9-AAV transfection to avoid the confounding effects of atherosclerosis and hyperlipidemia." (PMID 36194491, 2022). "Oil Red O staining showed considerable atherosclerotic lesions and intimal thickening in the ligated LCA from control mice following PCSK9 overexpression and PCAL; the extent of DF-induced atherosclerosis, by contrast, was significantly lower in Txndc5∆ECKO mice with PCSK9 overexpression." (PMID 35061532, 2022). "PCSK9 and APOC3 inhibitors have been successfully tested as treatments for atherosclerosis." (PMID 35677050, 2022).
atherosclerosis (continued). "The observed reduction in LDL-C levels of about 60% is comparable to what can be achieved by statins or PCSK9 antibodies, and the notion of sustained reductions in LDL-C might offer additional benefits as to the cumulative effects of LDL-C on atherosclerosis." (PMID 35050192, 2022). "In line with our findings, FATE also found a correlation between PCSK9 and VRFs, but failed to confirm any correlation with subclinical atherosclerosis observed in the small studies quoted above." (PMID 34356905, 2021). "Proprotein convertase subtilisin/kexin type 9 (PCSK9) has been gaining major attention after the emergence of data on the role of this protein in lipid homeostasis through regulation of low-density lipoprotein receptors and in atherosclerosis process." (PMID 35024053, 2021). "The clinical application of proprotein convertase subtilisin/kexin type 9 monoclonal antibody (PCSK9 inhibitor) has opened a new gate for lipid‐lowering therapy, but atherosclerosis is a chronic inflammatory process, and lipid‐lowering drugs cannot effectively reduce the inflammatory response." (PMID 34312998, 2021). "In addition, the proprotein convertase subtilisin/kexin type 9 (PCSK9), a well-known protein for its role in the LDL-R homeostasis and atherosclerosis progression, was shown to have a pro-inflammatory effect in macrophages." (PMID 33807807, 2021). "PCSK9 enhances platelet activation by binding to CD36, therefore contributing to atherosclerosis." (PMID 34071103, 2021). "Increased expression of PCSK9 is related to oxidized LDL-induced apoptosis in endothelial cell, which may give rise to subsequent endothelial dysfunction and pathogenesis of atherosclerosis." (PMID 33738300, 2021). "This conclusion was supported by studies that showed that in mice the absence of PCSK9 substantially reduces the development of atherosclerosis, apoB levels, and endothelial dysfunction and that its overexpression does the reverse." (PMID 34606887, 2021). "In fact, recent findings found that reduced ABCA1 expression in the macrophages, by proprotein convertase subtilisin/kexin type 9 (PCSK9), could accelerates atherosclerosis, thereby inhibiting RCT." (PMID 33766036, 2021). "Semaglutide does not promote regression of established atherosclerosis in PCSK9-AAV–treated HFHC diet–fed mice." (PMID 34673572, 2021). "Clinical data in CKD patients are scarce and not consistent regarding the role of PCSK9 in the inflammatory arm of atherosclerosis and on cardiovascular outcome." (PMID 34336112, 2021). "Regulation of cholesterol-rich LDL blood levels is not the only role that PCSK9 drives in atherosclerosis pathogenesis." (PMID 33834043, 2021). "The therapeutic inhibition of PCSK9 may have beneficial effects beyond LDL-C metabolism and atherosclerosis." (PMID 33304274, 2020). "Although multiple studies have identified pro-inflammatory effects of PCSK9 in promoting atherosclerosis, several studies have found that hs-CRP levels were not decreased despite the anti-inflammatory changes after treatment with PCSK9 inhibitors." (PMID 32169071, 2020). "The exogenously administered adeno-associated virus 8 (AAV8)-PCSK9 encoding a gain-of-function Pcsk9 mutant (D377Y) lacking the 3′-UTR region is commonly used to induce hyperlipidemia and experimental atherosclerosis in mouse models." (PMID 33119548, 2020).
atherosclerosis (continued). "Published research has shown that PCSK9 is involved in atherosclerosis via a variety of non-classical mechanisms that involve lysosomal, inflammatory, apoptotic, mitochondrial, and immune pathways." (PMID 32169071, 2020). "On the other hand, there is an increasing interest in the role of proprotein convertase subtilisin/kexin type 9 (PCSK9) in the pathophysiology of atherosclerosis, but there are no data about its relationship with CAE." (PMID 32967202, 2020). "The absence of PCSK9 in LDb mice results in decreased lipid and apoB levels, fewer atherogenic LDLs, and marked reduction of atherosclerosis." (PMID 29180444, 2018). "In this article, we are also focusing on the effects of PCSK9 inhibitor beyond LDL-C reduction like endothelial inflammation, atherosclerosis, its safety in patients with diabetes, obesity, and chronic kidney disease, and its influence on neurocognition and stroke." (PMID 29770231, 2018). "Here, in order to establish an atherosclerosis regression model independent of genetic background, we utilized a similar virus, expressing murine PCSK9 D377Y, under the control of thyroid-binding globulin (TBG) promoter, which is a liver specific promoter." (PMID 28291840, 2017). "Our data validate that reduced HDL cholesterol concentration and cholesterol efflux capacity in serum by Pcsk9 inactivation do not have significant impact on the early stage of atherosclerosis development." (PMID 23883163, 2013). "Moreover, given that atherosclerosis, the basic pathological change occurring in CVD, is primarily promoted by chronic inflammation induced by hyperlipidemia, the role of PCSK9 in inflammation has attracted the attention of many researchers in recent years." (PMID 39963241, 2025). "Treatment with the PCSK9 inhibitor SBC-115076 up-regulated ABCA1 and ABCG1 expression in plaque macrophages, restored cholesterol efflux capacity, reduced lipid deposition, and simultaneously lowered plasma Hcy levels while improving the lipid profile, thereby attenuating atherosclerosis severity." (PMID 41478627, 2025). "The expression level of PCSK9 was significantly elevated in the atherosclerosis control group (K+) compared with the negative control (K−), while the administration of C. lanatus extract, particularly at the highest dose (P3), significantly reduced PCSK9 levels (p < 0.001)." (PMID 40699832, 2025). "Within the vasculature, PCSK9 serves as a pivotal regulator of LDL-C levels and acts as a driver of atherosclerosis and subsequent atherosclerotic cardiovascular diseases (ASCVD)." (PMID 39139638, 2024). "In addition to its role in infectious sepsis and atherosclerosis, PCSK9 is involved in other noninfectious conditions, such as autoimmune diseases." (PMID 39736777, 2024).